CLDN5 (claudin 5)
Diseases named in the same sentence as CLDN5 in open-access papers (continued):
Sharing a sentence is not in itself a finding about the gene and the disease.
Alzheimer disease (21 papers, 2015 to 2025). A progressive, neurodegenerative disease characterized by loss of function and death of nerve cells in several areas of the brain leading to loss of cognitive function such as memory and language. "In Alzheimer’s disease (AD), the amyloid β-peptide was shown to induce changes in TJ and AJ proteins including claudin-5, occludin, ZO-1 and VE-cadherin causing dysfunction of the barrier and increased vascular permeability in AD patients." (PMID 35025943, 2022). "Similarly to occludin, claudin-5 has been described to be susceptible to the action of MMPs, as it was observed in an in vitro model of Alzheimer’s disease." (PMID 32867861, 2020). "Growing evidence implicates the dysregulation of Cldn5 in Alzheimer’s disease (AD), highlighting its emerging role in maintaining neurovascular integrity beyond classical amyloid and tau pathology." (PMID 40940757, 2025). "A similar decrease in proteins such as claudin-5, occludins, and zonula occludens-1 is also observed in the cortical areas of those suffering from Alzheimer’s disease." (PMID 38543885, 2024). "Transient modulation of claudin-5 expression using RNA interference has been shown to be beneficial in animal models of traumatic brain injury, Alzheimer’s disease and choroidal neovascularization." (PMID 34867185, 2021). "This study is the first to demonstrate the specific effects of iron overload on claudin-5 contributing a possible link between the paracellular permeability dysfunction and brain iron accumulation in certain diseases such as Alzheimer’s disease and Parkinson’s disease." (PMID 39939558, 2025). "For example, downregulation of CLDN5 in the brain allows for transfer of amyloid beta (Aβ), a primary indicator of Alzheimer’s disease, from the CNS into the periphery via the BBB; Aβ itself may autoregulate CLDN5 expression to allow for its clearance from the brain." (PMID 41358302, 2025). "Consistent with this, reduced CLDN5 expression and associated disruption to the BBB at the tight junctions is associated with numerous neurological conditions including traumatic brain injury sequela, Alzheimer’s disease, cognitive decline, multiple sclerosis, epilepsy, and stroke." (PMID 41358302, 2025). "Matrix metalloprotein-9 (MMP-9) and tight junction protein Claudin-5 have been shown to regulate BBB permeability and play an important role in neuropathologies such as Alzheimer’s disease." (PMID 32326620, 2020). "In the rat Alzheimer’s disease model, resveratrol defends BBB integrity by reducing advanced glycation end products (RAGE), matrix metalloprotein-9 (MMP-9) and increasing Claudin-5 but also reduces neuroinflammation by affecting nuclear factor NF-κB expression." (PMID 32326620, 2020). "Interestingly, Claudin 5 transcript has recently been shown to be significantly downregulated in FTD but not Huntington’s or Alzheimer’s disease choroid plexus." (PMID 32586411, 2020).
glioma (20 papers, 2013 to 2026). A benign or malignant brain and spinal cord tumor that arises from glial cells (astrocytes, oligodendrocytes, ependymal cells). "The main conclusion of the present study is that reduced expression CLDN1 and CLDN5 are linked to the advancement of malignant gliomas, with this effect becoming more evident as the grade of glioma increases." (PMID 41399659, 2026). "A correlation was observed between increased β-catenin and decreased CLDN5 expression in both patient glioma tissue and malignant glioma cells lines." (PMID 38147228, 2024). "The reduction of CLDN5 has increased the progression of glioma cells and the leakage of the brain-blood barrier (BBB)." (PMID 37286335, 2023). "Cldn5 expression is frequently altered in different human cancers, as CLDN5 gene was found to be downregulated in colorectal, liver, and lung cancer and glioma, suggestive for a potential tumor-suppressor role of CLDN5 in these cancer types." (PMID 32156068, 2020). "In contrast, silencing of miR-153 or miR-377 increased the expressions of ZO-1, occludin, and claudin-5 and decreased the permeability of glioma-conditioned normal BBB." (PMID 30305135, 2018). "The present study demonstrated that FOXR2 had high expression in GECs, and silencing of FOXR2 decreased the expressions of ZO-1, occludin, and claudin-5 and increased the permeability of glioma-conditioned normal BBB." (PMID 30305135, 2018). "Overexpression of piR-DQ590027 down-regulated the expressions of ZO-1, occludin, and claudin-5 and increased the permeability of glioma conditioned normal BBB." (PMID 30305135, 2018). "Overexpression of miR-153 or miR-377 reduced the expressions of ZO-1, occludin, and claudin-5 and further increased the permeability of glioma-conditioned normal BBB." (PMID 30305135, 2018). "We found that MIR17HG was highly expressed in GECs and MIR17HG silencing decreased the expressions of ZO-1, occludin, and claudin-5 and increased the permeability of glioma-conditioned normal BBB." (PMID 30305135, 2018). "Moreover, overexpression of CLDN3 support progression and metastasis of these malignancies, while reduced expression of CLDN1 and CLDN5 is observed in advanced gliomas." (PMID 41399659, 2026). "Downregulation of claudin-1, claudin-5, and occludin has been repeatedly reported in gliomas." (PMID 35910247, 2022). "Moreover, the expression levels of claudin-1 and claudin-5 decrease with increasing severity of the glioma, according to World Health Organization (WHO) grading." (PMID 35910247, 2022). "Thus, knockdown of this lncRNA reduces expression of tight junction proteins, such as ZO-1, occludin, and claudin-5 in glioma microvascular endothelial cells." (PMID 33980320, 2021). "This knockdown also decreased the levels of tight junction-correlated proteins, such as Zonula occludens 1 (ZO-1), occludin, and claudin-5, in glioma microvascular endothelial cells by targeting upstream stimulatory factor 1 (USF1), thus enabling drug delivery." (PMID 33980320, 2021). "Silencing of FOXR2 expression significantly decreased the mRNA and protein expression of ZO-1, occludin, and claudin-5, reduced their distribution in the cell membrane, and increased the permeability of glioma-conditioned normal BBB; FOXR2 overexpression had the opposite effects." (PMID 30305135, 2018). "Moreover, down-regulation of FOXR2 inhibited transcription and decreased the expressions of ZO-1, occludin and claudin-5, and further increased the permeability of glioma-conditioned normal BBB." (PMID 30305135, 2018). "Moreover, downregulation of FOXR2 decreases the transcription and thus the expressions of ZO-1, occludin, and claudin-5, and thereby increases the permeability of glioma-conditioned normal BBB." (PMID 30305135, 2018).
glioma (continued). "Our study showed that piR-DQ590027 can decrease the expression of ZO-1, claudin-5, and occludin and increase the permeability of glioma-conditioned normal BBB, suggesting that piR-DQ590027 overexpression increases the permeability of glioma-conditioned normal BBB via the paracellular pathway." (PMID 30305135, 2018). "Downregulation of claudin-3 and claudin-5 expressions in high-grade glioma has been reported." (PMID 28978116, 2017). "Similarly, by targeting runt-related transcriptional factor 1 (RUNX1), miR-18a downregulated mRNA of ZO-1, occludin, and claudin-5 in glioma vascular endothelial cells (GECs) and increased the permeability of BTB." (PMID 27999452, 2016). "In an in vitro co-culture model of RBE4 endothelial cells with U87 glioma cells, the levels of p-JNK and p-c-Jun were increased in RBE4 cells, while the expression of claudin-5 and ZO-1 was decreased compared with RBE4 cells cultured without U87." (PMID 40509244, 2025). "The expression of β-catenin gradually increased in higher glioma tumor grades, while the expression of TJ proteins CLDN1 and CLDN5 were both decreased." (PMID 38147228, 2024). "HOX transcript antisense intergenic RNA (HOTAIR) is up-regulated in gliomas, and HOTAIR combines with the promoter regions of occludin, ZO-1, and claudin-5 to promote their expressions, which decreases BBTB permeability." (PMID 33767583, 2021). "Finally, piR-DQ590027 is poorly expressed in glioma-conditioned ECs whereas piR-DQ590027 over-expression could decrease ZO-1, occludin, and claudin-5 expression to further increase glioma-conditioned normal BBB permeability through the piR-DQ590027/MIR17HG/miR-153(miR-377)/FOXR2 pathway." (PMID 31399034, 2019). "In glioma ECs, upregulation of miR-181a targeted Kruppel-like factor 6 (KLF6), downregulating ZO-1, occluding, and claudin-5, and increased permeability of the blood-tumor barrier (BTB)." (PMID 27999452, 2016). "Our next aim was to test if ReNcells CX injected into systemic circulation were able to reachintracerebral gliomas and to explore under this condition the expression of HGF, VEGF,zonulin/prehaptoglobin-2 and claudin-5." (PMID 23637756, 2013). "JNK inhibitor SP600125 could enhance the expression of claudin-5 and ZO-1 in RBE4 cells, which was inhibited by U87 glioma cells." (PMID 40509244, 2025). "Previous study suggested that NEAT1 was upregulated in glioma endothelial cells (CECs), knockdown of NEAT can increased blood-tumor barrier permeability through reducing the expression of TJ related proteins including ZO-1, Occludin, Claudin-5." (PMID 40338929, 2025). "Studies with human glioma endothelial cells showed that overexpression of miR-181a-5p reduces endothelial resistance and the gene expression of tight junction molecules OCLN, ZO-1 and CLDN-5." (PMID 33001231, 2021). "The expression of miR-181a is increased in glioma, and miR-181a can inhibit Kruppel-like factor 6 (KLF6) mRNA expression by directly binding to the 3' UTR of KLF6 mRNA; KLF6 can promote the transcriptional expressions of ZO-1, occludin, and claudin-5 mRNAs." (PMID 33767583, 2021). "The results indicate that piR-DQ590027 overexpression increases the permeability of glioma-conditioned normal BBB via the paracellular pathway by reducing the expressions of ZO-1, occludin, and claudin-5 in a manner that is related to the negative regulation of MIR17HG expression." (PMID 30305135, 2018). "This study showed that piR-DQ590027 was lowly expressed in glioma-conditioned ECs (GECs) and that piR-DQ590027 overexpression could decrease the expressions of ZO-1, occludin, and claudin-5 to further increase the permeability of glioma-conditioned normal BBB." (PMID 30305135, 2018).
glioma (continued). "It is conceivable, that in gliomas high levels of HDAC4 expression in complex with MEF2 acts as transcriptional repressor of KLF4 and, consequently, of zonula occluden-1, claudin-5, and occludin gene expression, which may be another important component in the mechanism of BBB disruption in gliomas." (PMID 30837601, 2019). "However, piR-DQ590027 silencing increased the expressions of ZO-1, occludin, and claudin-5 and thus reduced the permeability of glioma-conditioned normal BBB." (PMID 30305135, 2018).
breast cancer (19 papers, 2005 to 2025). A primary or metastatic malignant neoplasm involving the breast. "Yanget al. proved that high expression of CLDN5 is associated with better relapse free survival (RFS) in breast cancer." (PMID 38186223, 2024). "The expression of CLDN5 is associated with breast cancer cell motility, indicating the role of CLDN5 in the metastasis of human breast cancer." (PMID 37799140, 2023). "Claudin-5 is an important tight junction protein, which is highly expressed in breast cancer patients with high-risk metastasis and reoccurrence." (PMID 32182756, 2020). "Claudin-5 is a tight junction protein, which is highly expression in breast cancer patient with the high-risk metastasis and reoccurrence." (PMID 31182056, 2019). "A similar trend has been described in experimental models of brain metastases of breast cancer where there was a loss of ZO-1 and an increase in claudin-5 in the BTB." (PMID 31695842, 2019). "Claudin-5 has been found to be highly expressed in breast cancer patients with high-risk metastasis and reoccurrence." (PMID 31182056, 2019). "Claudin-5 is highly expressed in breast cancer patients with high-risk metastasis and reoccurrence." (PMID 32182756, 2020). "Collectively, these findings suggest that Claudin-5 is a potential prognostic factor in patients with breast cancer, as high levels of expression are clearly associated with indicators of poor prognosis as well as with high incidence of breast cancer-related death and shorter survival of patients." (PMID 22559840, 2012). "Disruption of the tight junction proteins (ZO-1 and claudin-5) by Ang-2 was shown to be partially dependent on the level of VEGF expressed by the breast cancer cells." (PMID 37190188, 2023). "The increased paracellular permeability, accompanied by changes in the immunostaining of tight junction protein claudin-5, was observed in cells treated with sera from breast cancer patients with cerebral and bone metastases." (PMID 34915908, 2021). "The mRNA of claudin-5 and occludin was decreased, while the mRNA of efflux pumps was increased after treatment with sera from breast cancer patients with primary cancer, cerebral and visceral metastases." (PMID 34915908, 2021). "Claudins are major adhesion molecules in tight junctions and are strongly expressed in various cancers, and claudin-5 is highly expressed in breast cancer patients." (PMID 32182756, 2020). "Loss of miR-202-3p in breast cancer cells enhanced their transmigration through the brain endothelium by upregulating MMP-1 and disrupting the inter-endothelial junctions (claudin-5, ZO-1 and ß-catenin)." (PMID 33002044, 2020). "Transepithelial resistance was measured to assess the effect of over-expressing or knocking-down Claudin-5 on TJ functionality in MDA-MB-231 breast cancer cells." (PMID 22559840, 2012). "We have shown for the first time that Claudin-5 is aberrantly expressed in human breast cancer and has a link to the clinical outcome of the patient." (PMID 22559840, 2012). "Patients who died from breast cancer had higher levels of Claudin-5 compared with patients who remained disease-free." (PMID 22559840, 2012). "Until now, we have shown that knockdown of Claudin-5 expression in a breast cancer cell line resulted in a less adhesive and less motile cell phenotype when compared to controls." (PMID 22559840, 2012). "It appears that Claudin-5 has a different role in breast cancer, functioning as a potential motility regulator." (PMID 22559840, 2012). "From the data presented here, we can reveal a link between Claudin-5 and cell motility in breast cancer cells." (PMID 22559840, 2012). "This study examined the level of expression and distribution of Claudin-5 in human breast cancer tissues and the effect of knockdown and forced expression of Claudin-5 in the MDA-MB-231 breast cancer cell line." (PMID 22559840, 2012). "We performed a further set of experiments to assess the level of involvement of Claudin-5 in breast cancer motility." (PMID 22559840, 2012).
breast cancer (continued). "The Claudin-5 gene was cloned and overexpressed or knocked down using ribozyme technology in human breast cancer cells." (PMID 22559840, 2012). "Following cloning and transfection, the human breast cancer cell line MDA-MB-231 was verified for Claudin-5 over-expression at both the mRNA using RT-PCR and protein levels using Western blot." (PMID 22559840, 2012). "Following confirmation of the levels of expression, the cells were used in a number of in vitro and in vivo experimental assays in order to clarify a possible role of Claudin-5 in breast cancer progression." (PMID 22559840, 2012). "This study portrays a very new and interesting role for Claudin-5 in cell motility involving the N-WASP signalling cascade indicating a possible role for Claudin-5 in the metastasis of human breast cancer." (PMID 22559840, 2012). "CLDN5 is tightly regulated at the blood-brain-barrier and is compromised in several neurological diseases, while in breast-cancer models, overexpression of CLDN20 increases trans-epithelial electrical resistance (TEER), both tissue-specific roles highlighting the complex nature of claudins." (PMID 40260206, 2025). "CLDN5 expression has been shown to be reduced in squamous cell carcinomas of the lung, cervical cancer, hepatocellular carcinoma, oral squamous cell carcinoma, breast cancer, and pancreatic cancer." (PMID 35281827, 2022). "A possible link has been revealed between claudin 5 and breast cancer metastases." (PMID 35453754, 2022). "Furthermore, Claudin-5 has potential as a prognostic tool in human breast cancer, in particular with relevance to patient survival and outcome." (PMID 22559840, 2012). "We might tentatively conclude from this that Claudin-5 might be a motility regulator, or at least have a role in the motility of these human breast cancer cells." (PMID 22559840, 2012). "The expression of Claudin-5 was examined in breast cancer specimens (tumour, n = 106; background, n = 27) using real-time quantitative Polymerase Chain Reaction (all values are displayed as mean Claudin-5 transcript copies/μL of cDNA from 50 ng total RNA and normalised by GAPDH)." (PMID 22559840, 2012). "Many questions still need to be answered and whilst high motility phenotypes might not lead to malignant progression per se, the control of motility by Claudin-5 could be a contributing factor to metastatic disease in human breast cancer." (PMID 22559840, 2012). "Although high levels of Claudin-5 have been reported in ovarian, prostate and lung cancers and low levels in hepatocellular carcinoma, this is the first study to our knowledge to report levels of Claudin-5 in patients with breast cancer." (PMID 22559840, 2012). "In addition, two classifier genes were identified (FHL1 and CLDN5) highly discriminative between most "normal" tissue samples and all breast cancer samples analyzed." (PMID 16091131, 2005). "Downregulating miR-202-3p enhanced the transmigration ability of breast cancer cells across the BE by mediating the expression of MMP1, which in turn degraded inter-endothelial protein junctions, ZO-1, claudin-5 and β-catenin." (PMID 37190188, 2023). "We then analyzed BMEC-tight junction proteins’ expression of ZO-1 and Claudin-5 in vivo in normal brain, as compared to TJs in tumor brains from syngeneic GFP-4T1-BrM5 mammary tumor cell model." (PMID 35351947, 2022). "Using the WT and QTRT1-KD MDA-MB-231 breast cancer cells, we showed the QTRT1-induced alterations of β-catenin and claudin-5." (PMID 32182756, 2020). "The use of a GPER agonists has been shown to increase the levels of claudin-5 in the ischemic CA1 in vivo and also increased levels of CD34 in mouse xenograft models of breast cancer." (PMID 29899833, 2018). "An important role of claudin-5 in cell motility through N-WASP and the ROCK signalling cascade has been shown in breast cancer cells." (PMID 26083392, 2015).
breast cancer (continued). "Furthermore, the less pronounced effects of MCF7CM on Occludin compared to Claudin-5 mRNA expression suggest that breast cancer cells target the Claudin-5 TJs pathways rather than Occludin." (PMID 34943153, 2021). "This discrepancy may be due to the non-discriminatory nature of Q-PCR, as we have not been able to specifically compare the levels of Claudin-5 in endothelial cells from normal mammary tissues and breast cancer tissues." (PMID 22559840, 2012). "In this present study, we used cells transfected with Claudin-5 expression sequence and ribozyme transgenes to assess the impact of reducing the expression of our protein of interest as well as enhancing it in order to evaluate changes in the aggressive nature of MDA-MB-231 breast cancer cells." (PMID 22559840, 2012).